MMP13 (matrix metallopeptidase 13)
Diseases named in the same sentence as MMP13 in open-access papers (continued):
Sharing a sentence is not in itself a finding about the gene and the disease.
neuronal tumor (1 paper, 2019). Neuronal brain tumors are an uncommon group of central nervous system tumors that arise from cells with neuronal differentiation. "In summary, these results show that the transcription factor FOXO3 binds to the MMP-9 and MMP-13 promoters and elevates the MMP-13 enzymatic activity in neuronal tumor cells." (PMID 31861249, 2019). "Hence, we investigated the impact of FOXO3 on MMP-9 and MMP-13 promoter activity in the aggressive neuronal tumor cell lines IMR32 and SK-N-SH." (PMID 31861249, 2019).
non-alcoholic steatohepatitis (1 paper, 2025). "In a mouse model of non-alcoholic steatohepatitis (NASH), SR9009 was reported to reduce glucose levels, improve glucose tolerance, and inhibit the expression of fibrotic markers, such as collagen α1(III) (COLl3A1), α-SMA, STAT1, MMP13, TIMP1, and TGF-β." (PMID 40255337, 2025).
Noonan syndrome (1 paper, 2020). Noonan Syndrome (NS) is characterized by short stature, typical facial dysmorphism and congenital heart defects. "In particular, skeletal dysplasias (ACAN, MMP13 mutations) and Noonan syndrome (PTPN11) were detected." (PMID 32939436, 2020).
oral diseases (1 paper, 2024). "As DDR1 has been verified to be significant in the development of dental and periodontal tissues and the process of oral diseases, in the present study, we focused on the mechanisms controlling DDR1-mediated MMP-1, MMP-2, and MMP-13 expression in hPDLCs to demonstrate the role of DDR1 in ERR." (PMID 39596178, 2024).
oropharyngeal tumour (1 paper, 2014). "Samples from 61 patients diagnosed with oropharyngeal tumour were studied by immunohistochemistry against MMP-2, MMP-7, MMP-9 and MMP-13." (PMID 26019601, 2014).
osteogenesis imperfecta (1 paper, 2013). Osteogenesis imperfecta (OI) comprises a heterogeneous group of genetic disorders characterized by increased bone fragility, low bone mass, and susceptibility to bone fractures with variable severity. "This indicates that hypomineralisation and lower collagen quantity / quality in Postn-/-, transfer the mechanical consequence of microcracks from toughness to stiffness, which to some degree is similar to the description made in osteogenesis imperfecta or in MMP-13 deficient mice." (PMID 24167618, 2013).
osteomyelitis (1 paper, 2019). An acute or chronic inflammation of the bone and its structures due to infection with pyogenic bacteria. "We have reported increased plasma levels of MMP-1 and MMP-13 in osteomyelitis patients in a previous work." (PMID 31647805, 2019). "CTSG N125S polymorphism was genotyped in 329 osteomyelitis patients and 415 controls), Blood coagulation parameters, serum CTSG activity, LF, MMP-1, MMP-13, and soluble receptor activator for nuclear factor κ B ligand (sRANKL) levels were assessed in carriers of the different CTSG genotypes." (PMID 31647805, 2019).
ovarian tumor (1 paper, 2010). "Possibly, MMP-13 is differentially expressed by OvCa cells and not crucial for ovarian tumor invasiveness per se." (PMID 20649989, 2010).
parasitic infection (1 paper, 2019). "MMP13 has been suggested to play a crucial role in inflammatory response of Atlantic salmon during salmon louse (Lepeophtheirus salmonis) parasitic infection." (PMID 31783772, 2019).
proliferative diabetic retinopathy (1 paper, 2023). Advanced retinopathy due to diabetes mellitus characterized by the formation of new vessels in the retina. "Upregulated MT1-MMP, with other proangiogenic factors such as MMP-2 and MMP-13, are associated with various progressive diseases, including tumor invasion, corneal neovascularization, and proliferative diabetic retinopathy via active neovascularization." (PMID 36768503, 2023).
pterygium (1 paper, 2017). A wedge-shaped fibrovascular lesion arising from the bulbar conjunctiva and extending to the cornea. "Furthermore, our results suggest that pterygium recurrence in vivo results from uncontrolled degradation of the ECM caused by an excess of MMP-13 in pterygium tissues." (PMID 28068383, 2017). "Next, the expression levels of MMP-3 and MMP-13 proteins were measured by western blot analysis using lysates of 3 normal conjunctiva tissues from 6 patients and of 4 pterygium tissues from 20 patients, as described in the Materials and Methods section." (PMID 28068383, 2017). "A previous study reported that the staining intensity of MMP-13 was greater in pterygium epithelial cells than in pterygium fibroblasts." (PMID 28068383, 2017). "In the present study, we have focused on the involvement of MMP-3 and MMP-13 in pterygium pathogenesis, and identified high levels of expression of both of these MMPs in migrating pterygium fibroblasts." (PMID 28068383, 2017). "The stained areas were 41.37-54.77% (MMP-3) and 54.81-71.90% (MMP-13) larger in the pterygium tissue than in the normal conjunctival tissue." (PMID 28068383, 2017). "Taken together, these findings suggest that MMP-3 and MMP-13 activities are both required for the migration of pterygium fibroblasts in the pathogenesis of pterygia." (PMID 28068383, 2017). "In the present study, a scratch wound assay was performed to evaluate the effects of MMP-3 and MMP-13 inhibition on the migration of pterygium-derived fibroblasts." (PMID 28068383, 2017). "Following normalization to β-actin expression, MMP-3 and MMP-13 levels increased by 1.7-fold and 3.02-fold (respectively) in pterygium tissue, as compared to their levels in conjunctiva tissue." (PMID 28068383, 2017). "Rates of cell migration from explant-cultured pterygia tissues and scratch-wounded confluent pterygium fibroblasts were examined in the presence of MMP-3 or MMP-13 inhibitors, as well as bevacizumab and/or CsA." (PMID 28068383, 2017). "The present in vivo and in vitro bevacizumab results indicate that there was a strong correlation between the inhibition of MMP-3 and MMP-13 expression by bevacizumab and the inhibition of pterygium fibroblast migration." (PMID 28068383, 2017). "MMP-13 was stained intensely in the basal and columnar epithelium, particularly in the regions of fragmented BL, adjacent to pterygium fibroblasts." (PMID 28068383, 2017). "Recently, we reported that CsA down-regulated MMP-3 and MMP-13 expression in cultured pterygium fibroblasts." (PMID 28068383, 2017). "Interestingly, expression of both MMP-3 and MMP-13 proteins was detected in the epithelium and stroma of the pterygium tissue, but these were weakly expressed in normal conjunctival tissue." (PMID 28068383, 2017). "In addition, we demonstrated that combined treatment with bevacizumab and/or CsA down-regulated both MMP-3 and MMP-13 expression and greatly decreased pterygium fibroblast migration, confirming that these activities are necessary for this process." (PMID 28068383, 2017). "Although many MMPs were expressed in pterygium tissues, our study mainly focused the activities of MMP-3 and MMP-13 which may play an important role in the process of pterygium progression." (PMID 28068383, 2017). "Notably, as compared to the MMP-3 staining pattern, more intense MMP-13 staining was detected in the superficial epithelial layer of the pterygium tissue." (PMID 28068383, 2017). "Interestingly, similar to the bevacizumab effects, CsA produced a significant reduction in MMP-3 and MMP-13 expression and in pterygium fibroblast migration." (PMID 28068383, 2017). "Importantly, exposure to potent inhibitors of MMP-3 or MMP-13 activity suppressed the migration of cells from cultured pterygium tissues and of cultured pterygium fibroblasts." (PMID 28068383, 2017).
pterygium (continued). "The fibroblasts migrating from pterygium tissue explants produced both MMP-3 and MMP-13 proteins, and we therefore examined whether inhibition of either of these activities affected fibroblast outgrowth from the explanted pterygium for 2 days (0 h)." (PMID 28068383, 2017). "Importantly, combined CsA and bevacizumab produced a larger inhibition of MMP-3 and MMP-13 expression and of pterygium fibroblast migration, as compared to treatment with bevacizumab or CsA alone." (PMID 28068383, 2017). "Furthermore, we examined the effects of CsA on MMP-3 and MMP-13 expression in pterygium fibroblasts 24 h after the scratch wound was made." (PMID 28068383, 2017). "Importantly, the present study found that treatment with MMP-3 or MMP-13 inhibitors reduced the migration of fibroblasts from cultured pterygium tissues and into a scrape wound." (PMID 28068383, 2017). "Therefore, we suggest that MMP-13 expressed by pterygium tissues may induce collagen II and III remodeling in pterygium stroma." (PMID 28068383, 2017). "Although the detailed mechanisms involved in bevacizumab-mediated inhibition of MMP-3 and MMP-13 expression and pterygium fibroblast migration are currently unknown, the present study suggests that bevacizumab could make an important contribution to the management of pterygia." (PMID 28068383, 2017). "Taken together, these data indicate that fibroblast outgrowth from the pterygium tissue edge was mediated, at least in part, by MMP-3 and MMP-13." (PMID 28068383, 2017). "In contrast, the intensity of both protein bands was significantly reduced in the pterygium tissues treated with bevacizumab (MMP-3, 0.13-fold; MMP-13, 1.27-fold), as compared to pterygium tissue from untreated patients." (PMID 28068383, 2017). "However, the present data suggest that increased expression of MMP-3 and MMP-13 by pterygium fibroblasts may be involved in the pathogenesis of pterygium, and combination treatment with bevacizumab and CsA therefore represents a potential therapy for pterygium recurrence." (PMID 28068383, 2017). "In the pterygium tissue, MMP-3 and MMP-13 expression levels were significantly stronger than those observed in normal conjunctival tissues." (PMID 28068383, 2017). "Based on the immunohistochemical data, we examined whether fibroblasts migrating from the pterygium explant culture expressed high levels of MMP-3 and MMP-13." (PMID 28068383, 2017). "Taken together, these results suggest that CsA may inhibit the migration of pterygium fibroblasts by down-regulating both MMP-3 and MMP-13." (PMID 28068383, 2017).
pulmonary TB (1 paper, 2021). "MMP-1 and its activator MMP-3 were found to be related to the TB disease severity and treatment efficacy, while MMP-13 together with TIMP-2 were proved to be potential indicators of extra-pulmonary TB in adults." (PMID 33923293, 2021).
renal carcinoma (1 paper, 2020). A carcinoma arising from the epithelium of the renal parenchyma or the renal pelvis. "Previous investigations have indicated that COL1A1 and MMP13 are associated with cancer metastasis, and TM-induced apoptosis also showed close association with GRP78 and MMP13 in renal carcinoma cells." (PMID 33014334, 2020).
rickets (1 paper, 2021). Bone softening and weakening usually caused by deficiency or impaired metabolism of vitamin D. Deficiency of calcium, magnesium, or phosphorus may also cause rickets. "We report a new pathogenic heterozygous variant in MMP13 (NM_002427.4: c.216G>C, p.Gln72His) in a toddler, initially thought to have rickets, and his father, with MAD phenotypes." (PMID 34022834, 2021).
root caries (1 paper, 2023). Dental caries involving the tooth root, cementum, or cervical area of the tooth. "MMP-13 may be increased in root caries when compared to coronal, but the evidence is very uncertain." (PMID 38029242, 2023). "It has to be noted that no MMP-13 activity was observed in the crown region by western blot methods, suggesting its exclusive presence in root caries lesions." (PMID 38029242, 2023). "MMP-13 increased in root caries, and absent in coronal caries." (PMID 38029242, 2023).
skin aging (1 paper, 2023). The gradual irreversible changes in structure of skin that occur as a result of the passage of time.. "Hence, blocking MMP13 and MMP12 would enhance skin elasticity and protect against skin aging." (PMID 37746045, 2023).
small cell carcinoma (1 paper, 2008). A neuroendocrine carcinoma composed of small malignant cells which are often said to resemble "oat cells" under the microscope. "In the stratified analysis by histological types, we observed that homozygotes for variant allele of polymorphisms in MMP1 and MMP13 genes increase the risk of developing small cell carcinoma." (PMID 19094243, 2008).
spinal stenosis (1 paper, 2009). Narrowing of the spinal canal. "The expressions of active MMP-2 and MMP-13 were significantly higher in the spinal stenosis samples than that in the disc herniation samples (both p < 0.05)." (PMID 19885059, 2009). "Immunohistochemical analysis demonstrated that MMP-2, MMP-3, and MMP-13 were positively stained on the ligamentum flavum fibroblasts of the patients with spinal stenosis and disc herniation, respectively." (PMID 19885059, 2009). "We also found that there was a higher expression of MMP-13 in the spinal stenosis samples compared with that of the disc herniation samples (p < 0.05)." (PMID 19885059, 2009). "Western blot analysis demonstrated the expressions of active MMP-2, MMP-3, and MMP-13 in the ligamentum flavum specimens of the spinal stenosis patients and the disc herniation patients." (PMID 19885059, 2009). "The mean density (arbitrary units) of active MMP-2 and MMP-13 was statistically higher in the spinal stenosis specimens than that in the disc herniation specimens (324.75 ± 63.66 vs. 238.00 ± 76.05, respectively, p < 0.05; 340.00 ± 48.63 vs. 248.50 ± 52.09, respectively, p < 0.05)." (PMID 19885059, 2009). "While we found increases of MMP-2 and MMP-13 in the spinal stenosis samples, this does not necessarily mean that these factors are either solely or even partially responsible for the histologic changes associated with the clinical condition." (PMID 19885059, 2009).
steatosis (1 paper, 2015). Increased lipid within the cytoplasm of cells. "We found that Mmp12 (P < 0.001) and Mmp13 (P < 0.05) were significantly upregulated in the liver of mice with steatosis compared to normal livers using 2-way ANOVA followed by the Bonferroni post-test." (PMID 25880591, 2015). "Immunohistochemical analysis of MMP13 expression shows staining of MMP13 with steatosis in the murine liver and varied distribution of the protein in both stromal cells as well as hepatocytes in human patient samples with NAFLD." (PMID 25880591, 2015). "Mmp13−/− mice developed steatosis comparable to the wildtype counterparts." (PMID 25880591, 2015). "Thus, MMP13 is elevated both in human NAFLD as well as in a mouse model of diet induced steatosis." (PMID 25880591, 2015).
synucleinopathies (1 paper, 2020). "To better understand the role of MMP13 in synucleinopathies, we further characterized the role of MMP13 in microglial signaling." (PMID 33343280, 2020).
tear (1 paper, 2019). "Brophy’ findings suggested that the expression level of MMP13 was higher in patients with a combined meniscal and ACL tear compared with the patients with only meniscal tear." (PMID 31787088, 2019).
tongue (1 paper, 2014). "The second study which mainly focused on oral tongue SCC found a significant role for MMP13 as a prognostic marker." (PMID 25401159, 2014).
vascular tumours (1 paper, 2017). "MMP‐13 degrades ECM components, including Ln‐5, continuously promoting endothelial cell migration in the ECM, the release of VEGF and bFGF, and ultimately the generation of endothelium‐dependent vascular tumours." (PMID 28766880, 2017).
viral infection (1 paper, 2025). "The CXCL10/11high basal cells also had upregulated mRNA encoding for complement components (C1R and C1S), MHC class I (HLA-A, HLA-B, HLA-C, and B2M), and metalloproteases MMP2 and MMP13, the latter reducing repair during viral infection in bronchial epithelial cells." (PMID 40980495, 2025).
xeroderma pigmentosum (1 paper, 2021). Xeroderma pigmentosum (XP) is a rare genodermatosis characterized by extreme sensitivity to ultraviolet (UV)-induced changes in the skin and eyes, and multiple skin cancers. "They did not observe differences in the MMP-13 expression between the two groups, but when analyzing the Ki67 expression, they detected higher levels in those with xeroderma pigmentosum, which may explain the more aggressive behavior of these tumors in patients with xeroderma pigmentosum." (PMID 34204372, 2021).
ZIKV infection (1 paper, 2019). "Increased MMP10 and MMP13 are further supporting the notion that ZIKV infection promotes inflammation and extracellular remodeling." (PMID 31249527, 2019).